METTL17 (methyltransferase like 17)
Description:
Mitochondrial ribosome (mitoribosome) assembly factor. Binds at the interface of the head and body domains of the mitochondrial small ribosomal subunit (mt-SSU), occluding the mRNA channel and preventing compaction of the head domain towards the body. Probable inactive methyltransferase: retains the characteristic folding and ability to bind S-adenosyl-L-methionine, but it probably lost its methyltransferase activity.
Synonyms: METT11D1; FLJ20859
Tractability: Small molecule: a structure with a bound ligand is known. PROTAC: ubiquitination databases record sites on it; its protein half-life has been measured.
Gene: Protein-coding gene on chromosome 14 (20,989,973 to 20,997,035, forward strand). Ensembl gene ENSG00000165792.
Subcellular location: Mitochondrion matrix
Subcellular location (Human Protein Atlas): Nucleoplasm
Gene Ontology:
Molecular function: 4 iron, 4 sulfur cluster binding; methyltransferase activity; protein binding; S-adenosyl-L-methionine binding; mitochondrial ribosome binding; small molecule binding
Biological process: mitochondrial small ribosomal subunit assembly; ribosomal small subunit biogenesis; translation
Cellular component: mitochondrion; nucleoplasm; mitochondrial matrix; intracellular organelle lumen
Genetic constraint (gnomAD): Loss-of-function variants: 46 observed, 56.26 expected, observed/expected ratio (o/e) 0.82, 90% interval 0.64 to 1.04. The upper end of that interval is the gene's LOEUF score, 1.04, which puts it in group 4 of 6, group 1 being the genes least tolerant of losing a copy. Missense variants: 543 observed, 594.02 expected, observed/expected ratio (o/e) 0.91, 90% interval 0.85 to 0.98. Synonymous variants: 205 observed, 215.67 expected, observed/expected ratio (o/e) 0.95, 90% interval 0.85 to 1.07.
Homologues: Orthologues: chimpanzee METTL17 (99% identical), macaque METTL17 (95% identical), pig METTL17 (85% identical), rat Mettl17 (81% identical), rabbit METTL17 (80% identical), mouse Mettl17 (80% identical), dog METTL17 (79% identical), tropical clawed frog mettl17 (55% identical), zebrafish mettl17 (45% identical), Drosophila melanogaster CG13126 (30% identical). Paralogues in human: COX11 (12% identical).
Diseases named in the same sentence as METTL17 in open-access papers:
METTL17 is named in the same sentence as 18 diseases in open-access papers, as found by Europe PMC text mining. Sharing a sentence is not in itself a finding about the gene and the disease. The quoted sentences say what the papers report.
colorectal cancer (4 papers, 2024 to 2025). A primary or metastatic malignant neoplasm that affects the colon or rectum. "This study reveals that the mitochondrial protein METTL17 governs mitochondrial function in colorectal cancer (CRC) cells through epigenetic modulation." (PMID 38377789, 2024). "The Cancer Genome Atlas (TCGA) analysis unveiled an up-regulation of METTL17 mRNA in colorectal cancer (CRC) tissues compared to normal colorectal tissues." (PMID 38377789, 2024). "Here, we investigate the biochemical mechanisms and molecular functions of METTL17 in ferroptosis regulation and cell survival determination of colorectal cancer (CRC)." (PMID 38377789, 2024). "RNA modification of METTL17 in mitochondria of colorectal carcinoma leads to decreased iron death activity in tumor cells and promotes tumor proliferation." (PMID 39160604, 2024).
Alzheimer disease (1 paper, 2021). A progressive, neurodegenerative disease characterized by loss of function and death of nerve cells in several areas of the brain leading to loss of cognitive function such as memory and language. "The inhibition of methyltransferases that are functionally or structurally related to METTL17 rescued synaptic and cognitive functions for Alzheimer’s disease." (PMID 34182925, 2021).
breast carcinoma (1 paper, 2024). "METTL17 can act as a coactivator of ERs, and inhibition of METTL17 leads to reduced transcriptional activity of ERα and ERβ in breast cancer cells, reduces the expression of ER target genes and limits the growth of breast cancer cells." (PMID 38429907, 2024).
colitis (1 paper, 2024). Inflammation of the colon. "To evaluate the impact of METTL17 in CRC tumorigenesis in vivo, we conducted a xenograft tumor model and an AOM/DSS-induced murine colitis-associated CRC model." (PMID 38377789, 2024).
colorectal tumors (1 paper, 2024). "Next, we assessed the cell proliferation rate and malignancy grade through Ki-67 and β-Catenin immunostaining of colorectal tumors from both WT and Mettl17+/− mice." (PMID 38377789, 2024).
Friedreich ataxia (1 paper, 2024). An inherited condition that affects the nervous system and causes movement problems. "Overexpression of METTL17 rectifies the bioenergetic deficits of Friedreich’s ataxia." (PMID 38199006, 2024).
lung carcinoma (1 paper, 2018). "For example, our data indicate that METTL17 loss significantly suppresses human lung cancer cell growth and support the idea that the identification of energy-modulating genes could inform the development of cancer-relevant biochemical approaches." (PMID 30148842, 2018).
cancer (6 papers, 2018 to 2024). A tumor composed of atypical neoplastic, often pleomorphic cells that invade other tissues. "Consistently, DepMap analysis revealed a strong correlation in gene effect between METTL17 and LRPPRC, MRPS9, MRPS22, and MRPS35, highlighting the significance of METTL17-associated cellular functions in cancer cell survival and ferroptosis defense." (PMID 38377789, 2024). "Furthermore, we found that the knockdown of METTL17 significantly inhibited the glucose uptake ability of cancer cells, indicating impaired glucose supply in METTL17 loss cells." (PMID 38377789, 2024). "Moreover, our findings reveal that targeting the METTL17-associated pan-mitochondrial translation regulation could expand our current concept of ferroptosis vulnerability in cancer therapy." (PMID 38377789, 2024). "Furthermore, while METTL17 has been implicated in coactivating with estrogen receptors and regulating breast tumorigenesis, its functions in other cancers remains largely unknown." (PMID 38377789, 2024). "Bioinformatic analysis establishes that METTL17 expression positively correlates with ferroptosis resistance in cancer cells and is up-regulated in CRC." (PMID 38377789, 2024). "Remarkably, similar to METTL17 knockdown experiments, the knockdown of these METTL17-interacting proteins sensitized cancer cells to ML162-induced ferroptosis and inhibited cell proliferation in CRC." (PMID 38377789, 2024). "This indicates that METTL17 is necessary for maintaining regular mitochondrial gene expression in cancer cells." (PMID 38377789, 2024). "Concurrently, intracellular and mitochondrial ROS levels were significantly elevated in METTL17 knockdown cancer cells following ML162 treatment, as demonstrated by DCFH-DA and MitoSOX staining." (PMID 38377789, 2024). "To elucidate the mechanisms underlying the METTL17's impact on ferroptosis sensitivity and CRC development, we investigated the cellular distribution and function of METTL17 in cancer cells." (PMID 38377789, 2024). "Based on our bioinformatics analysis from the DepMap database, most of METTL17 co-dependent genes coordinate mitochondrial gene expression in cancer cells." (PMID 38377789, 2024). "In summary, loss-of-function screens of cancer cell lines support the biological importance of several METTLs, notably METTL1, METTL3, METTL14, METTL16 and METTL17, in promoting cancer cell growth and survival." (PMID 34285249, 2021). "Further, comprehensive analysis of another two databases, Cancer Dependency Map (DepMap) and Cancer Cell Line Encyclopedia (CCLE), demonstrate that the protein level of METTL17 is positively associated to ML162 and RSL3 AUC drug sensitivity across various cancer cell lines." (PMID 38377789, 2024). "This promising approach suggests that manipulating mitochondrial gene expression could be a viable strategy for cancer treatment, opening the door to METTL17 as a potential target for therapy." (PMID 38377789, 2024). "However, it is unclear whether METTL17 is required for mitochondrial gene expression in cancer cells." (PMID 38377789, 2024).
tumor (5 papers, 2018 to 2025). "Loss of METTL17 significantly impairs mitochondrial protein translation and inhibits the mitochondrial oxidative respiratory chain; notably, METTL17 deficiency has also been reported to suppress tumor proliferation." (PMID 41154608, 2025). "Here, we demonstrate for the first time that high expression of mitochondrial METTL17 in tumor cells is positively correlated with resistance to ferroptosis inducers, which broadens the understanding of mitochondria-mediated ferroptosis." (PMID 38377789, 2024). "However, the precise mechanisms through which METTL17 mediates various tumor pathways necessitate further exploration." (PMID 38377789, 2024). "Interestingly, we showed that Mettl17+/− protected mice from AOM/DSS-induced CRC tumorigenesis as evidenced by reduced tumor size and tumor number." (PMID 38377789, 2024). "Depletion of METTL17 sensitizes CRC cells to ferroptosis, impairs cell proliferation, migration, invasion, xenograft tumor growth, and AOM/DSS-induced CRC tumorigenesis." (PMID 38377789, 2024). "Indeed, METTL17 knockdown sensitized SW620 xenograft tumors to ML162 treatment, showcasing a synergistic effect for CRC therapy, as evidenced by the decrease in tumor volume, size and weight." (PMID 38377789, 2024).
infection (2 papers, 2020 to 2024). The state of being infected such as from the introduction of a foreign agent such as serum, vaccine, antigenic substance or organism. "GNG7 and METTL17 have been identified as potential host factors for the infection of cyprinid herpesvirus 2 (CyHV-2) and HIV-1." (PMID 38542067, 2024).
mitochondrial disease (1 paper, 2023). "The investigation of METTL17 and other mitochondrialribosome assembly factors is of both fundamental and practical significance,because defects in mitochondrial ribosome assembly are often associated withhuman mitochondrial diseases." (PMID 38234605, 2023).
METTL17 also shares sentences with these, for which no sentence is quoted: benign adenoma (1 paper); chronic kidney disease (1); colon cancer (1); leukemia (1); osteosarcoma (1); renal fibrosis (1); Ureteral obstruction (1).